EGF (epidermal growth factor)
Diseases named in the same sentence as EGF in open-access papers (continued):
Sharing a sentence is not in itself a finding about the gene and the disease.
ulcer (continued). "The guide of the Colombian Diabetic Foot Group (COLPEDIS), within the treatment options of ulcers generated by this disease, includes the recombinant human epidermal growth factor (rhEGF), as an adjuvant in ulcer care to achieve better healing times." (PMID 29963295, 2018). "EGF has been reported to be a major factor involved in the repair mechanism of ulcer healing and the management of the return to normal mucosal function." (PMID 30298136, 2018). "In this experiment, the rate of ulcer healing in rats in scorpion peptide gel group was faster than that in epidermal growth factor group, which obviously began from the second week after the ulcer induction." (PMID 29234410, 2017). "It is also known that treatment of stressed rats with epidermal growth factor (EGF), results in an ulcer index significantly lower than that in stressed rats treated with vehicle." (PMID 29149074, 2017). "Numerous experimental and epidemiological investigations supplied strong evidences that EGF/EGFR signaling pathway played a pivotal role in ulcer repair." (PMID 23825635, 2013). "The increase is expected since ulcer healing would require more EGF for an effective signal transduction." (PMID 18237397, 2008). "On the other hand, following the establishment of infection and the appearance of an ulcer, the expression level of EGF and platelet growth factor (PDEGF) drastically decreased, and with the onset of treatment and during the wound healing process, their expression gradually increased." (PMID 39808642, 2025). "It has been established that EGF, VEGF, IL-6, and TNF-α are crucial factors in the development of gastric ulcers, and their levels are associated with the healing or deterioration of these ulcers." (PMID 38398633, 2024). "Additionally, levels of gastric protective mediators, such as prostaglandin E2 (PGE2), epidermal growth factor (EGF), and EGF receptor, which are known to promote ulcer healing, were also elevated through alginate intervention." (PMID 39517244, 2024). "Furthermore, EGF supplements are effective in ulcer healing and have positive effects of EGF in ulcer prevention." (PMID 37727361, 2023). "Moreover, the anthocyanidin accelerated the healing of acetic acid-induced ulcer, increased the gene expression of EGF and COX-1, and downregulated MMP-9." (PMID 34684313, 2021). "This novel dual DDS allows for the synchronous release of GS and EGF and may serve as a faster and efficient therapy for the treatment of intractable ulcers." (PMID 30993143, 2019). "The epidermal growth factor (EGF) is recognized medicine of therapy in ulcer." (PMID 29234410, 2017). "Topical EGF or other growth factors have been reported in smaller and/or less advanced ulcers." (PMID 24004460, 2013). "It has been reported that the enhancement of cell proliferation during ulcer healing may be mediated by increased release of EGF and TGF-α." (PMID 24192345, 2013). "The endogenous EGF level stimulation by PK is promising for its use as an anti-ulcer agent." (PMID 18237397, 2008). "The role of the endogenous EGF in ulcer healing is also unequivocally confirmed." (PMID 18237397, 2008). "EGF ranks first in healing rate and healing time, second to PDGF in ulcer area reduction, and PRP ranks first in amputation rate and incidence of AEs." (PMID 40636711, 2025). "In this study, the EGF, VEGF-A, and PGE2 levels were measured in gastric homogenates to evaluate angiogenesis, mucosal integrity, and ulcer prevention." (PMID 41036937, 2025). "In diabetic foot ulcers, PDGF-BB and EGF, together with PRP, consistently improve complete healing and reduce ulcer area." (PMID 41375885, 2025). "The EGF, VEGF-A, and PGE2 levels were measured in gastric homogenates to evaluate angiogenesis, mucosal integrity, and ulcer prevention." (PMID 41036937, 2025). "Compared to SOC, EGF, PDGF, and PRP significantly improved healing rates; EGF and PRP significantly reduced healing time; and PDGF significantly decreased ulcer area." (PMID 40636711, 2025).
ulcer (continued). "In the present work, in the PANTO-treated group, 14 days after the induction of GU, the intensity of EGF expression in the gastric tissue showed moderate immunopositivity, indicating the reasonable effect of PANTO toward ulcer healing." (PMID 38652367, 2024). "In the hamsters with improvement of their ulcers, the expression levels increased 0.011 ± 0.017 times for PDGF, 17.5 ± 2.4, for EGF, 0.01 ± 0.03 for FGF, and 2.1 ± 0.1 for TGFβ1." (PMID 30333964, 2018). "Likewise, FCL dramatically raised EGF and KGF relative gene expression, demonstrating its beneficial impact in ulcer healing." (PMID 41329690, 2025). "EGF and PRP also significantly reduced healing time, while PDGF significantly reduced ulcer area." (PMID 40636711, 2025). "For ulcer area reduction, PDGF, EGF, and PRP were the top-ranking interventions." (PMID 40636711, 2025). "The antioxidant, anti-inflammatory, and anti-apoptotic effects of LG, its ability to regulate EGF, VEGF-A, and PGE2 levels, and its capacity to reduce blood glucose levels in diabetic rats may contribute to its anti-ulcer effect." (PMID 41036937, 2025). "In addition, FCL significantly increased EGF and KGF relative gene expression, showing its favorable effect on ulcer healing." (PMID 41329690, 2025). "Overall, they showed a significant relationship between salivary EGF and RAS-induced ulcer healing." (PMID 37727361, 2023). "More recently, chronic wounds were found to exhibit decreased levels of EGF, providing rationale to deliver EGF to chronic, non-healing ulcers." (PMID 30993143, 2019). "Therefore, there is reason to believe that the application of Nal-P-113 advanced the time at which HIOECs primarily produced EGF and FGF-2 and decreased TGF-β1, thus promoting oral ulcer healing." (PMID 30298136, 2018). "Although APF and HB-EGF levels were similar in ulcerative and nonulcerative IC patients, EGF levels were significantly higher in IC patients with vs. without ulcers (p < 0.004)." (PMID 15862132, 2005). "Epidermal growth factor (RR 3.83; 95% CrI 1.81, 9.10), plasma‐rich protein (PRP) (RR 3.36; 95% CrI 1.66, 8.03) and platelet‐derived growth factor (PDGF) (RR 2.47; 95% CrI 1.23, 5.17) significantly improved the likelihood of complete ulcer healing compared to control." (PMID 37277960, 2023). "Additionally, EGF supports the healing process of chronic wounds, non-healing chronic wounds and ulcers, which are, for example, observed in diabetic patients known to lack the necessary growth factors to maintain the healing process." (PMID 28324162, 2019). "EGF and EGFR could inhibit the secretion of gastric acid, and their autocrine system plays an important role in cell proliferation and differentiation during ulcer healing." (PMID 26978395, 2016). "Furthermore, EGF is the ligand of EGFR, which is secreted in the gastrointestinal tract and could facilitate epithelial cell repair, reduce gastric acid secretion and promote the healing of ulcers." (PMID 32276345, 2020). "Furthermore, we have found higher levels of EGF and VEGF in all those groups of rats whose ulcers healed as compared to those groups whose ulcers did not healed." (PMID 34961769, 2021). "Although multiple studies have analyzed susceptibility and resistance genes associated to the development of the lesions, the role of EGF, FGF, and PDGF in the establishment of the infection, development of the ulcer, and in early response to treatment has not been established." (PMID 30333964, 2018).
COVID-19 (48 papers, 2020 to 2025). A disease caused by infection with severe acute respiratory syndrome coronavirus 2. "EGF was also among the 30 soluble factors identified in patients who survived COVID-19, in whom elevated EGF levels were observed, suggesting an association with survival." (PMID 41301889, 2025). "Plasma miR-144, possibly in combination with IL-10 and EGF, emerges as a flexible noninvasive tool for risk-based stratification and mortality prediction of COVID-19 patients." (PMID 36414650, 2022). "In conclusion, circulating miR-144-3p, possibly in combination with IL-10 or EGF, emerges as a noninvasive tool for early risk-based stratification and mortality prediction in COVID-19." (PMID 36414650, 2022). "Our results are in line with previous studies in COVID-19-hospitalized patients, indicating that elevated levels of urinary EGF are associated with a lower risk of AKI stage 3, new dialysis initiations or death." (PMID 36499745, 2022). "Recent studies involving AKI patients hospitalized with COVID-19 have shed light on the association between urinary EGF and adverse kidney outcomes, suggesting the potential for use of urinary EGF as a tool for tracking progression and recovery in kidney disease patients." (PMID 38732362, 2024). "Thus, plasma EGF could be closely linked with inflammatory response of innate and adaptive immunity and reflect the severity of COVID-19." (PMID 36012146, 2022). "EREG has been identified as a critical mediator of IL-6/IL-17-induced upregulation of several EGF members and has been previously identified in COVID-19 as a correlate of inflammation." (PMID 37452024, 2023). "We determined elevated levels of EGF in patients with severe COVID-19 compared to patients with moderate disease." (PMID 36012146, 2022). "Concentrations of EGF in the blood plasma of patients with COVID-19 showed an increase in this cytokine for the Wuhan strain; other variants show no indication of hypercytokinemia in terms of EGF." (PMID 36430621, 2022). "Regardless of the existence of a direct interaction of miR-144 with IL-10 and EGF, we found that combined scores increased discriminatory power of disease severity and the prediction of mortality in COVID-19 patients, providing a robust stratification tool." (PMID 36414650, 2022). "Recently, it was shown that EGF concentration was higher in plasma from patients with critical COVID-19." (PMID 36012146, 2022). "In this study, the patients with moderate and severe COVID-19 significantly differed from each other based on the levels of three cytokines eotaxin, IL-12p40, and EGF." (PMID 36012146, 2022). "As a next step towards understanding the mechanisms of EGFR-signaling implementation in the COVID-19-related severity, we stimulated A549 and H1299 cells with the recombinant EGF before the addition of lentiviral particles." (PMID 34045585, 2021). "Plasma concentrations of amphiregulin, an epidermal growth factor produced by damaged epithelial cells that promotes lung repair, were elevated in patients with COVID-19." (PMID 34648357, 2021). "Our study demonstrates that the levels of IL-6, IL-8, IL-10, VEGF, MCP-1 and EGF were significantly increased in the severe COVID-19 patients." (PMID 34868558, 2021). "We show that plasma CXCL2, CXCL10, CCL5, CD40 ligand, IL-10, and GM-CSF concentrations and ELF CXCL1, CXCL10, granzyme B, TRAIL, and EGF concentrations were found in greater concentrations in COVID-19 than in non-COVID-19 ARDS patients." (PMID 33138839, 2020). "A trend toward higher ELF concentrations of CXCL1 (p = 0.287), CXCL10 (p = 0.287), granzyme B (p = 0.110), TRAIL (p = 0.094), and EGF (p = 0.094) is observed in COVID-19 patients." (PMID 33138839, 2020). "In addition, IGF1 and EGF were central nodes and are both factors that influence various biological processes in COVID-19." (PMID 41227320, 2025).
COVID-19 (continued). "A large number of activated pro-inflammatory cytokines and chemokines were found in the serum of patients with severe COVID-19, including the membrane forms of epidermal growth factor (EGF) family members, IL-6 receptor, and TNF-α, and developed into a strong cytokine storm." (PMID 38138990, 2023). "Decreased EGF expression in COVID-19 patients with subclinical AKI might reflect low renal reserve and histological damage without these being clinically evident." (PMID 36499745, 2022). "Furthermore, EGF was considered to be a marker of repair after either muscle or kidney tissue injury in patients with severe COVID-19." (PMID 36012146, 2022). "Also, EGF is likely implemented in the immune cells attraction to the damaged lung in the severe COVID-19 patients." (PMID 34045585, 2021). "Additionally, levels of EGF were increased in COVID-19 patients, especially aged patients, compared to healthy donors and positively correlated with BMI in young COVID-19 patients." (PMID 34707619, 2021). "Studies show that EGF and TGF-β1 expression increases with COVID-19 severity, while their serum levels paradoxically decrease in critical cases." (PMID 40943354, 2025). "Our approach also relies on controlled delivery of hepatocyte regenerative stimuli, HGF and EGF, to the liver using mRNA-LNP23,24, which has been validated as clinically safe with the recent mRNA-based COVID-19 vaccines." (PMID 38866762, 2024). "Consistent with reports of fibrotic lung abnormalities following SARS-CoV-2 infection, patients with COVID-19 had significantly higher concentrations of multiple epidermal and platelet-derived growth factors, including TGF-α, EGF, PDGF-AB/BB, and PDGF-AA30." (PMID 38368384, 2024). "In a study involving 294 COVID-19 patients, the analysis revealed key post-COVID cytokines—FGF-2, VEGF-A, EGF, IL-12(p70), IL-13, and IL-6—crucial for understanding pathophysiology." (PMID 38793604, 2024). "These tight interactions and pathological connections between EGF signaling and the TLR system play a crucial role in current respiratory syncytial (RS)-virus-induced and COVID-19-induced cytokine storm and pneumonia." (PMID 36830741, 2023). "We successfully identified the shared 6 candidate gene signatures (RRM2, EGF, TMEM252, RARRES1, COL6A3, CUBN) between COVID-19 and AKI." (PMID 37789254, 2023). "The results revealed that 6 key gene signatures (RRM2, EGF, TMEM252, RARRES1, COL6A3, CUBN) were recognized to have great influences on COVID-19 and AKI." (PMID 37789254, 2023). "Sex differences in the number of classical monocytes (cMono), epidermal growth factor (EGF), and Eotaxin-1 became apparent in female versus male COVID-19 patients." (PMID 37998327, 2023). "Elevations in the EGF, FGF2, VEGFA, sVEGFR1, sVEGFR2, sVEGFR3, PDGFAA, PDGFABBB and sEGFR repair factors have been observed in patients with COVID-19." (PMID 36142255, 2022). "The lower serum levels of the repair factor FGF2 and the higher levels of PDGFABBB, EGF and PDGFAA had significant predictive value for a good prognosis in severe COVID-19 patients." (PMID 36142255, 2022). "One upregulated DEG (EGF) and one downregulated DEG (IFNAR2) have been uncovered in COVID-19 responses in BD." (PMID 35185890, 2022). "Compared with influenza, serum EGF, LF, and CD40L were higher in serum from patients with critical COVID-19, while G-CSF was lower." (PMID 35216673, 2022). "In male participants, EGF, GM-CSF, IL-1ra, IL-1α, IL-1β, IL-2, IL-4, IL-7, IL-15, EOTAXIN, MDC, MIP-1α, MIP-1β, IFNα2, and sCD40L were significantly lower in COVID-19 patients compared to controls." (PMID 36554094, 2022). "Our results thus confirm that EGF indeed is involved in the infection processes of the lung cells and EGFR signaling is a potential drug target in COVID-19 treatment." (PMID 34045585, 2021). "While in serum, low levels of EGF, Flt-3L, MDC and IL-12p70 in serum were distinctive to PCR-confirmed COVID-19 and PCR-/IgG+ SARI participants." (PMID 34117221, 2021).
COVID-19 (continued). "Serum EGF and CD40L levels were elevated in COVID-19 patients who survived compared to patients who died or healthy controls." (PMID 34529726, 2021). "Their effects in COVID-19 patients could be part of hyperinflammation for MAPK3, whereas IGF1 and EGF signaling if overactivated it can lead to fibrosis." (PMID 41227320, 2025). "Another smaller study (n = 113) that featured only individuals with moderate and severe COVID-19, found a similar enrichment of VEGF, EGF and PDGF in those with moderate disease and low mortality, when measured within an early subset (<12 days from symptom onset)." (PMID 39144942, 2024). "Moreover, patients with severe COVID-19 had higher concentrations of EGF and TGF-α, suggesting concurrent activation of pro-fibrotic epidermal growth factor pathways within the first week of illness." (PMID 38368384, 2024). "In the severe COVID-19 cohort, HIF signaling could likely be triggered by IL-6, IFNγ and growth factors (VEGF and/or EGF) as ligands of receptor tyrosine kinases." (PMID 37301958, 2023). "In contrast, EGF, GDF, and SEMA3 signaling pathways were unique to mild/moderate COVID-19." (PMID 37936693, 2023). "Hypoxic conditions occurring in acute COVID-19 could induce growth factors such as VEGF, PDGF, EGF and IGF, ultimately potentiating cell proliferation in the vascular bed, and may hold true for those patients with “happy hypoxia” (or local tissue hypoxia)." (PMID 37301958, 2023). "On the other hand, comparing non-critical vs. critical COVID-19 patients, EGF levels were found to be significantly (adj." (PMID 36414650, 2022). "We also tested the levels of IL-10 and EGF mRNAs in PBMCs of COVID-19 patients and controls, but none significant differences were observed." (PMID 36414650, 2022). "Serum levels of EGF, G-CSF, GM-CSF, IL-1ra, IL-1α, IL-1β, IL-2, IL-4, IL-7, IL-8, EOTAXIN, fractalkine, GRO, P-10, MDC, MIP-1α, MIP-1β, IFNα2, and sCD40L were significantly lower in female COVID-19 patients compared to controls." (PMID 36554094, 2022). "Tocilizumab is a potent inhibitor of IL-8 and IL-6 and inhibits angiogenesis, however to what extent it inhibits EGF in COVID-19 is not known." (PMID 35930528, 2022). "Regarding growth factors, the levels of platelet derived growth factor (PDGF-AA) and epidermal growth factor (EGF) were higher in pregnant COVID-19 compared with pregnant without COVID-19." (PMID 34326336, 2021). "The underlying mechanisms of the pathogenesis and infection of S-COVID-19 could be better described by suggesting APP, EGF, C3, APOE, and APOA1 as the novel chief organizers of the network foundation." (PMID 33244380, 2020). "IGF1 and EGF support tissue repair after lung injury from SARS-CoV-2, aiding regeneration, but dysregulation of these factors may impair recovery, contributing to fibrosis, particularly in severe COVID-19 or long COVID." (PMID 41227320, 2025). "In our study, the levels of seven cytokines in COVID-19 patients (IL-6, IP-10, IL-8, MIG, MIP-1β, IL-18, TNF-α) were different from those in healthy controls, while M-CSF, MCP-1, FLT-3, VEGF, IL-1RA, EGF, eotaxin and MCP-1 were not different." (PMID 34539644, 2021).